TRGVB (T cell receptor gamma variable B (pseudogene))
Synonyms: V6P; TCRGVB
Gene: T-cell receptor variable (V) pseudogene on chromosome 7 (38,295,763 to 38,296,233, reverse strand). Ensembl gene ENSG00000231202.
Diseases named in the same sentence as TRGVB in open-access papers:
TRGVB is named in the same sentence as 2 diseases in open-access papers, as found by Europe PMC text mining. Sharing a sentence is not in itself a finding about the gene and the disease.
TRGVB shares sentences with these, for which no sentence is quoted: prostate tumors (1 paper); tumor (1).